ENSG00000207177
Synonyms: LOC124900207
Gene: Small nucleolar RNA gene on chromosome 5 (110,684,794 to 110,684,927, reverse strand). Ensembl gene ENSG00000207177.
Gene Ontology:
Biological process: RNA processing
Cellular component: nucleolus
Homologues: Paralogues in human: SNORA51 (85% identical).